APRG1 (APRG1 tumor suppressor candidate)
Synonyms: C3orf35
Gene: Long non-coding RNA gene on chromosome 3 (37,381,062 to 37,440,186, forward strand). Ensembl gene ENSG00000198590.
Subcellular location: Membrane
Diseases named in the same sentence as APRG1 in open-access papers:
APRG1 is named in the same sentence as 6 diseases in open-access papers, as found by Europe PMC text mining. Sharing a sentence is not in itself a finding about the gene and the disease. The quoted sentences say what the papers report.
osteosarcoma (2 papers, 2020 to 2022). A usually aggressive malignant bone-forming mesenchymal neoplasm, predominantly affecting adolescents and young adults. "C3orf35, also known as APRG1, was associated with poor prognosis of osteosarcoma and may affect tumor metastasis and immune cell infiltration in osteosarcoma patients." (PMID 36233294, 2022).
breast carcinoma (1 paper, 2024). "C3orf35 is an alias and previous HGNC symbol for the APRG1 tumor suppressor candidate which is an RNA gene with little known properties or associations beyond a study in 2005 that it may suppress tumor growth in breast cancer." (PMID 38584916, 2024).
APRG1 also shares sentences with these, for which no sentence is quoted: cancer (3 papers); tumor (3); brain cancer (1); leukemia (1).